EEA1 (early endosome antigen 1)
Diseases named in the same sentence as EEA1 in open-access papers (continued):
Sharing a sentence is not in itself a finding about the gene and the disease.
trisomy 21 (1 paper, 2021). A chromosomal disorder consisting of the presence of an extra chromosome 21. "In cells with and without trisomy 21, the extent of colocalization of FcRn with the endosomal marker EEA1 was ~ 40% (PCC DS: 0.40 ± 0.10, PCC NDS: 0.43 ± 0.12), and the extent of colocalization of FcRn with LAMP1 was ~ 10% (PCC DS: 0.10 ± 0.05, PCC NDS: 0.09 ± 0.03)." (PMID 34040082, 2021).
infection (84 papers, 2008 to 2025). The state of being infected such as from the introduction of a foreign agent such as serum, vaccine, antigenic substance or organism. "As expected, simultaneous knockdown of all three Rab5 isoforms in BMDMS reduced the number of EEA1‐positive compartments associated with ΔsdhA LCV during infection." (PMID 32096265, 2020). "The association of markers for early (EEA1, Rab5) and late (Rab7) endosomes with B. pseudomallei phagosomes were assessed from 0.5 to 4 h after infection." (PMID 31199852, 2019). "Interestingly, EC (ATP1B3) exhibited higher expression of phagocytosis-related genes in TNBC patients, RAB5A and EEA1, indicating these patients could be more susceptible to infection." (PMID 35265720, 2022). "In this study, transcriptomic sequencing revealed that the expression level of EEA1 changed significantly after 12 h of cell infection with GpCDT." (PMID 41244687, 2025). "The quantification of r values within the range of 0.6–0.9 demonstrated a moderate-to-strong correlation of HAdVs and EEA1/Rab5 at the indicated time points after infection." (PMID 38392896, 2024). "At 15 min after infection, 7.5% of all wild-type HAdV2 particles introduced into the cell were found to be colocalized with the EEA1 protein." (PMID 38392896, 2024). "By confocal microscopy, ARM and WE strains have similar intracellular trafficking although LCMV-ARM infection appears to coincide with greater co-localization of early endosome marker EEA1 with TLR-2." (PMID 38675975, 2024). "Nevertheless, there seemed to be a small but noticeable increase in the co-staining of EEA1 with TLR-2 in LCMV-ARM-infected cells compared to LCMV-WE or mock infection." (PMID 38675975, 2024). "In fact, the ASFV virion colocalizes with EEA1 at early post-infection times and, at later time points, colocalization of the viral cores with Rab 7 positive late endosomes has been reported." (PMID 37243184, 2023). "Approximately, 80% of the ACVs of A. baumannii clinical isolate 398 colocalized with EEA1 as early as 15 min post infection (mpi), however, the percentage of colocalization of this marker decreased over time." (PMID 37294840, 2023). "We observed the greatest amount of RSV colocalization with EEA1 90 min after infection which aligns with the previous report." (PMID 38015055, 2023). "Our data shows that Cdc42 depleted cells had significantly less filopodia, lower infection compared to control infection, and decreased overlap between PsVs and EEA1." (PMID 35746622, 2022). "A previous report has shown that PRRSV virions were internalized into early endosomes for productive infection and colocalized with early endosomes (marked by early endosome antigen 1 [EEA1]) at 30 min postinfection." (PMID 35080428, 2022). "Preventing particle transit through EEA1-positive early endosomes and Rab7-positive late endosomes prevents a productive infection." (PMID 35320319, 2022). "After 20 min of infection, S. aureus was detected in EEA1-positive phagosomes and in Rab5-positive phagosomes of both CAP-treated and untreated macrophages." (PMID 34133202, 2021). "Namely, Rab5a was highly recruited at EE organelles before infection, EEA1 was mainly found on dispersed vesicles, whereas Vps34 and Hrs were hardly detectable on endosomes in uninfected cells." (PMID 34575026, 2021). "GFP-LVS-infected macrophages in the presence of naïve or LVS-immune lymphocytes 48 h after infection were stained with markers of the endosomal (EEA1 and LAMP1), lysosomal (Cathepsin D and Lysotracker), and autophagic pathways (LC3B)." (PMID 32694562, 2020). "In summary, our study shows, for the first time, that H-1PV internalisation occurs via clathrin-mediated and dynamin-dependent endocytosis, while requiring endosomal acidification, with EEA1 and Rab7 involved in the infection process." (PMID 33096814, 2020).
infection (continued). "We focused on mouse macrophages between 24 and 74 h after infection, using confocal microscopy coupled with staining for markers for the endosomal (EEA1 and LAMP1), autophagic (LC3B), and lysosomal (Cathepsin D and Lysotracker) pathways." (PMID 32694562, 2020). "Internalized EGFRs were extensively co-localized with markers for early (EEA1 and Hrs) endosomes at 8 to 10 h post-infection, suggesting EGFRs trafficked to these compartments prior to degradation." (PMID 31425554, 2019). "We examined co-localization of virions and cellular proteins (clathrin, caveolin, endophilin, EEA1) at several time points post-infection (p.i.)." (PMID 31053158, 2019). "The early phagosome marker EEA1 showed strong colocalization with Mtb during the early phase of infection, whereas inhibition of p38 MAPK with SB203580 reduced the colocalization of EEA1 with Mtb in LPC-treated cells." (PMID 29755479, 2018). "To determine if infection alters the frequency of this association, we analyzed ARF6 and EEA1 localization under steady-state conditions in both uninfected and HCMV-infected cells." (PMID 30042195, 2018). "At 30 and 60 min after infection, the percentage of EEA1-positive compartments containing GAS in NLRX1 KO cells was significantly increased compared to that in wild-type cells." (PMID 30488027, 2018). "In sharp contrast, the frequency of coincidence of CD147 with EEA1 increased over time during infection similarly to the CD59 results." (PMID 30042195, 2018). "Of note, the EEA1-positive endosomes were enlarged in the context of infection (up to 1 μm), consistent with the observations of other groups." (PMID 30042195, 2018). "Shortly after infection (5–30 mpi), capsid and inner envelope proteins are detected in early endosomes or macropinosomes, colocalizing with specific markers such as EEA1 and Rab5." (PMID 29117102, 2017). "Our automated analysis showed that on average, more than 50% of NP+ signals were EEA1+ at 5 min, with the frequencies dropping to the lowest at 4 h post infection." (PMID 28591131, 2017). "A large number of intracellular U. parvum colocalized with EEA1 30 min after infection, but this colocalization decreased after 3 hr." (PMID 28088841, 2017). "When HeLa or HaCaT cells were infected with wild-type HPV16.L2F and stained for L2-FLAG in proximity to EEA1, a PLA signal was detected at eight hours post-infection, and by 16 hours the PLA signal associated with this compartment was reduced." (PMID 25693203, 2015). "An L2/EEA1 PLA signal was observed in cells infected with HPV16.L2DM at eight hours after infection." (PMID 25693203, 2015). "In contrast to what has been published for the DC Mtb phagosome, very few Mtb (4.9+/−2.7%) or Msm (5.4+/−2.1%) were associated with the early endosomal marker Rab5, or its effector EEA1 (1.8+/−1.8% for Mtb and 12.1+/−2.7% for Msm) 4 hours following infection." (PMID 24828674, 2014). "For pUL78, a partial colocalization with EEA1 was already shown at 48 h post infection in a previous report." (PMID 24517969, 2014). "At different duration of infection, the cells were fixed and immuno-stained using EEA1, CD63 and GM130 as markers of early endosomes, late endo(lyso)somes, and Golgi apparatus, respectively." (PMID 23382959, 2013). "Immunofluorescence staining showed that, during HPIV1 infection, the C proteins co-localized with endogenous Alix whereas neither protein co-localized with the early endosomal marker EEA1." (PMID 23527201, 2013). "At 20 minutes post infection, the mean fraction of virus particles colocalized with early endosomes (marked by EEA1) was ∼50% and ∼53% for control and CD81-knockdown cells, respectively." (PMID 24130495, 2013). "At 8 hr post-infection an average of 23% of VipA colocalized with EEA-1 and 40% with actin filaments, being these values approximately 10% higher in the case of the strain carrying Ptac-vipA+." (PMID 22383880, 2012).
infection (continued). "In contrast, there was a decrease in the amount of EEA1 that was co-localised with E. coli DH5α phagosomes from a high immediately after infection to a low at the 15 and 30 minute time-points." (PMID 21426584, 2011). "The amount of Rab5 associated with H. pylori NL101 phagosomes increased at 15 and 30 minutes after infection before reaching a level similar to that seen for EEA1 at two hours and four hours after infection (NL101)." (PMID 21426584, 2011). "H. pylori NL101 phagosomes showed a substantially higher amount of co-localisation with EEA1 than with Rab5 immediately after infection." (PMID 21426584, 2011). "At two and four hours after infection, the amount of EEA1 co-localised with E. coli DH5α phagosomes was equivalent to that seen for Rab5 (ECOL)." (PMID 21426584, 2011). "In normal mammary tissue CD44+/CD24−/low stem cells TLR9 localized in endosomes in Ad5/3-Delta24 infected cells, as indicated by colocalization with an endosomal marker EEA1 and persisted still in the endosomes 6 h after infection." (PMID 21079774, 2010). "We found that the ECV is EEA1 positive for up to 1 h post infection and progresses to being VATPase positive from 3 h to 12 h post infection." (PMID 20011125, 2009). "Fifteen minutes after infection the majority (∼65%) of the intracellular bacteria co-localized with the early endosomal marker EEA-1." (PMID 18225954, 2008). "For this, following HRV16 challenge or mock infection, we first stained hMDMs for EEA1." (PMID 38332148, 2024). "Early endosomal antigen-1 (EEA1) could be seen for both WT and ΔinlB bacteria, but only at 10 min after infection and for a small proportion of LCVs (~10%) (left)." (PMID 36656016, 2023). "Our data supports our original hypothesis that if infection was increased in cells treated with drug and virus then the overlap between PsVs and EEA1 would be increased as well." (PMID 35746622, 2022). "HPV infection caused a marked redistribution of JX2 and EEA1 to discrete punctate structures with substantial overlap, whereas the distribution of FA did not change upon infection." (PMID 32521275, 2020). "Consistent with previous reports, LVS tagged with a fluorescent reporter (GFP-LVS or mCherry-LVS) was phagocytosed by macrophages and began to escape from EEA1+ or LAMP1+ phagosomes within 1 to 2 h of infection (illustrating partial LVS colocalization with LAMP1 by 4 h after infection)." (PMID 32694562, 2020). "Interestingly, while Tfn, Rab5a and EEA1 showed very low levels of clustering at infection sites, Rab11a displayed significantly higher clustering at these sites." (PMID 31242273, 2019). "If cargo such as MHC-I or CD98 was directed by infection into EEA1 membranes of a heterotypic SE, then it might be shielded or out of the reach of TRE17, which specifically associates with ARF6-GDP." (PMID 30042195, 2018). "The early phagosome marker, EEA1, and the late phagosome marker, lysosomal-associated membrane protein 1 (LAMP-1), showed a consistently increased ratio of colocalization with FITC-labeled Mtb-containing phagosomes throughout H37Ra or H37Rv infection." (PMID 29755479, 2018). "As early as 2 h post-infection most bacteria were excluded from the endosomal compartment and only ~34% of bacteria were found in compartments labeled for the early endosomal antigen 1 (EEA-1)." (PMID 29963502, 2018). "We demonstrated that U. parvum and EEA1 colocalization 30 min after infection." (PMID 28088841, 2017). "In addition, we also found that latex beads containing phagosomes are clearly separated from Rab5a and EEA1 positive Leishmania-PV in macrophages after 24 h of infection." (PMID 28650977, 2017). "In contrast, the pUS27 signal colocalized with EEA1 in HFFs only at late times of infection." (PMID 24517969, 2014).
infection (continued). "Furthermore, we detected a clear colocalization of pUL78 with EEA1 immediately upon expression, whereas pUS27 started to colocalize with the marker for early endosomes (EEs) at late time points after infection (96 hpi) only in HFFs." (PMID 24517969, 2014). "In order to examine the colocalization of translocated VipA during the course of infection with endosomes and actin, infected cells were stained with respectively, an anti-EEA-1 antibody and rhodamine-phalloidin, a fluorescently-labeled protein that specifically binds F-actin." (PMID 22383880, 2012). "For H. pylori NL107, Rab5 and EEA1 co-localisation with phagosomes increased over the first thirty minutes following infection, decreased between 30 minutes and two hours, before stabilising at a low level at two to four hours after infection (NL107)." (PMID 21426584, 2011). "Additionally, Rab4b and EEA1 also play a crucial role in the virus’s infection." (PMID 41244687, 2025). "We still saw infection and overlap of virus with EEA1 after ML-141 inhibition of Cdc42 and siRNA targeted treatments, albeit significantly decreased, which suggests that Cdc42 may not be essential for viral entry into cells but potentially in viral trafficking." (PMID 35746622, 2022). "Consequently, to test whether the virus enters the cell by endocytosis, we examined co-localization of viral particles with early endosome antigen 1 (EEA1) at different times post-infection (pi)." (PMID 29970183, 2018). "Similarly, when expression of EEA1 was measured in murine macrophages infected with Paracoccidioides brasiliensis, EEA1 protein was present in the early endosome, in the first hours of infection, but strongly decreased after the fungus was internalized." (PMID 29547649, 2018). "Compared to phagosomes containing H37Rv or the complemented strain, which avoid EEA1 localization, phagosomes containing the secA2 mutant exhibited significantly higher EEA1 co-localization at both 1hr and 24hrs post infection (i. e. time following a 4hr period of initial uptake/infection)." (PMID 29709019, 2018). "The virus localized to the endocytic pathway, as visualized by co-localization of virus N-protein with EEA1, as already shown for Hantaan virus in Vero-E6 cells, while the membrane ruffling visible at later time points of infection could be an additional sign of high endocytic activity." (PMID 28943870, 2017). "As infection proceeded, SERINC5 translocated sequentially to early endosome (EEA1), late endosome (Rab7) and lysosome (LAMP1)." (PMID 36223419, 2022). "At 2 h after infection with the wt strain, the colocalization of the FCP with the early endosomal marker EEA1 was only 5.4% and with LAMP-1 8.51%, indicating that the majority of F. novicida were either in the cytosol or in a compartment lacking these markers." (PMID 35077486, 2022). "For instance, EspF recruits clathrin, AP2, early (Rab5a and EEA1) and recycling (Rab4a, Rab11a, Rab11b, FIP2, Myo5b) endocytic proteins to sites of infection." (PMID 31947656, 2020). "Confocal microscopy analysis showed that H-1PV co-localised with EEA1, Rab7 and LAMP-1 markers during infection." (PMID 33096814, 2020). "We therefore investigated the T3SS dependence of the distribution of clathrin endocytic (CHC, AP2-α, Rab5a and EEA1) and recycling [Rab11a, Rab11b, Rab25, Myosin 5b (Myo5b)] components upon EPEC infection of polarized MDCK cells." (PMID 31242273, 2019). "We show that type-III secreted components prompt the recruitment of clathrin (clathrin and AP2), early (Rab5a and EEA1) and recycling (Rab4a, Rab11a, Rab11b, FIP2, Myo5b) endocytic machineries to peripheral plasma membrane infection sites." (PMID 31242273, 2019). "Heterotypic ARF6/EEA1 vesicles were also enlarged in HCMV-infected cells compared to uninfected cells, suggesting that infection exaggerates this structure." (PMID 30042195, 2018).
infection (continued). "HPV16 PsVs were found to localize to early endosomes at 4 hours post infection (hpi) at comparable levels in DCT knockdown and control cells as detected by the overlap of the green (EEA1) and red (H16.V5) signal." (PMID 28095444, 2017). "There was a gradual increase in the levels of H. pylori-induced EEA-1 and LAMP-1 expression, and a concurrent increase in the conversion of LC3-I to LC3-II, over the course of the infection." (PMID 28144585, 2016). "When the BMDMs were analyzed at 3 h after infection, many FITC-labeled M. tuberculosis bacteria (both H37Ra and H37Rv) were co-localized with EEA1 in all three mouse BMDM strains." (PMID 27148227, 2016). "After 15 min of infection with YpIII p(IB604), a band recognized by anti-V mAb was observed in the fraction that also was detected by EEA-1 Ab (180 kD)." (PMID 19609450, 2009). "Time-lapse fluorescence microscopy images showed that, in the absence of diphenoxylate, N efficiently colocalized with EEA1 at 0.5 h post-infection." (PMID 38742905, 2024). "We again found that GAS was initially located in phagosomes, as indicated by EEA-1 staining, which was followed by rapid bacterial colocalization with the mature lysosomal marker LAMP-2 within the first 15 min of infection, similar to the colocalization dynamics observed with LAMP-1 staining." (PMID 38722166, 2024). "MDBK cells incubated with BRSV at 4°C for 1 h were transferred to 37°C for 30 min, the localization of EEA1 and BRSV G protein was analyzed by IFA and confocal microscopy, the result showed clear co-localization of EEA1 and BRSV G protein after 30 min of infection." (PMID 38690369, 2024). "Shortly after infection, the ASFV virions enter into cells via clathrin-mediated endocytosis (CME) and the capsid protein p72 can be detected in early endosomes colocalizing with specific markers such as EEA1 and Rab5A." (PMID 39024394, 2024). "Following a 24-h infection period, analysis of acceptor cells indicated that a majority of fibrils co-localized with LAMP1 (< 30%), while smaller amounts of fibrils co-localized with EEA1 (3%) and Vamp3 (< 30%)." (PMID 35909452, 2022). "At 30 min post-infection, GBS colocalized with EEA-1, a marker of early endosomes." (PMID 34129624, 2021). "Both EEA-1 and LAMP were found to colocalize with leptospires after infection." (PMID 33123147, 2020). "Infection with EPEC-espF+EspF and EPEC-map+Map evoked a sharp decrease in perinuclear Tfn-positive endosomal area, a concomitant increase in Tfn/TfnR and Tfn/EEA1 intensity in the peripheral endosomes, and an increase in Tfn endocytic turnover." (PMID 31242273, 2019). "Furthermore, the percentage of EEA1- and Rab7-positive compartments containing GAS in Beclin 1 and UVRAG KO cells decreased significantly, compared to that in wild-type cells during infection." (PMID 30488027, 2018). "After the FMDV-containing macropinosomes were dissociated from the plasma membrane, they were soon colocalized with EEA1-labeled early vesicles but did not colocalize with LAMP1-positive late vesicles during the whole infection period." (PMID 26757826, 2016). "However, at 16 hours post-infection, the L2/TGN46 PLA signal was essentially undetectable, whereas there was a striking increase in the L2/EEA1 PLA signal." (PMID 25693203, 2015). "Here, we demonstrate that co-localization of pUL78 signal with that of EEA1 is not restricted to the 48 h post infection time point, but in fact occurs throughout the HCMV replication cycle in HFFs as well as in ARPE-19 cells (data not shown)." (PMID 24517969, 2014). "In the absence of PrPC, the mRNA expression of Rab5, Rab7, and Eea1 in BMDMs increased after infection with E. coli." (PMID 25058617, 2014). "At the times of infection (1h, 5h, 24 h) investigated C. jejuni only rarely co-localized with EEA1-positive early endosomal compartments and did not seem to be specifically localized in close vicinity of the Golgi apparatus." (PMID 23382959, 2013).